CD44 (CD44 molecule (IN blood group))
Diseases named in the same sentence as CD44 in open-access papers (continued):
Sharing a sentence is not in itself a finding about the gene and the disease.
breast carcinoma (continued). "CD44 cDNA vaccination has been shown to decrease tumor mass and metastatic potential in experimental mammary tumors in mice." (PMID 21541039, 2011). "In mammary cancer cells, the interaction among HA, CD44, and EMMPRIN potentially regulates the localization and function of the plasma membrane transporter, as well as the tumor MDR." (PMID 21749678, 2011). "In breast cancer, miR-373 and miR-520c promote tumor invasion and metastasis in vivo and in vitro by the suppression of CD44." (PMID 20209130, 2010). "For instance, in breast cancer, the ALDHhi marker appears to identify more CSCs than the classical CD44+CD24−/lo markers." (PMID 21072210, 2010). "The first breakthrough for CSCs in solid tumor systems was in breast cancer, where Al-Hajj analyzed breast cancer stem cells using CD44 and CD24 as markers." (PMID 24281178, 2010). "A recent report implicates novel gene sets in oncogenic Ras, TNF and IFN pathways in breast cancer CD44+/CD24−/low populations." (PMID 21079774, 2010). "CD44 facilitates breast cancer progression through alterations of tumor cell adhesion characteristics." (PMID 20374665, 2010). "Using a mammosphere culture technique, MCF7 mammosphere cells are found to enrich breast cancer stem-like cells expressing CD44+CD24-." (PMID 20569497, 2010). "One cell adhesion molecule identified was CD44, which has been directly correlated to human breast cancer grade." (PMID 20591176, 2010). "In mammary carcinomas, CD44+CD24low cells were invasive in vitro but the phenotype was not sufficient for metastasis when cells were injected intracardiacally in vivo." (PMID 21067584, 2010). "A broad range of the egfr gene copy numbers leading to different EGFR expression levels can be found simultaneously under normal cell culture conditions in the breast cancer cell line MDA-MB-468 CD44+/CD24-/LOW." (PMID 20199686, 2010). "Antibody-mediated CD44 targeting has inhibited growth of breast cancer xenografts and prevented regrowth of basal-like HBCx cells after chemotherapy-induced remission." (PMID 20736947, 2010). "Primary human breast cancer cells are immuno-phenotypically heterogeneous and CD44+ subpopulations are tumorigenic in NOD/SCID mice bearing estrogen pellets." (PMID 24281098, 2010). "Far beyond these genetic properties MDA-MB-468 CD44+/CD24-/LOW is a valuable model for studies in breast cancer progression because it is likely to represent a basal-like/stemness cell phenotype of breast cancer." (PMID 20199686, 2010). "The expression profiles of stem-like cells from normal and neoplastic breast tissue were highly similar, and both expressed numerous stem cell markers, whereas both normal and breast cancer CD24+/CD44+/− cells had features of luminal differentiation." (PMID 24281098, 2010). "There is an overlap with those genes found in a previous report using cells from CD24−/low/CD44+ and CD24+/CD44+ populations derived from normal breast and primary breast cancer tissues." (PMID 19997106, 2010). "For breast cancer, CD44+/CD24-/low and aldehyde dehydrogenase (ALDH) have been reported as markers for breast cancer stem cells." (PMID 21044318, 2010). "Breast cancer stem cells (BCSCs) have been recently identified in breast carcinoma as CD44+CD24- cells, which exclusively retain tumorigenic activity and display stem cell-like properties." (PMID 20569497, 2010). "We demonstrated that breast cancer cells with CD44+/CD24- phenotype express elevated levels of invasion-associated genes and are invasive but this phenotype is not a requisite for homing and growth at sites of metastasis." (PMID 20691079, 2010). "Previous studies in both breast cancer cells and tissues have shown that breast cancer stem cells are cells with an ESA+CD44+CD24-/low phenotype." (PMID 21192833, 2010).
breast carcinoma (continued). "Regardless the proportion of T-ICs, FACS-sorted CD44+/CD24− cells that derived from primary tumors or breast cancer lines were about 10–60 fold more resistant to chemotherapy relative to the non- CD44+/CD24− cells and their parental cells." (PMID 21187973, 2010). "Breast cancer cells with CD44+/CD24- cell surface marker expression profile are proposed as cancer stem cells (CSCs)." (PMID 20691079, 2010). "For example, in breast cancer, the CD44+/CD24−/low sub-population, which comprises ∼11–35% of the total cell population, has been shown to be the population of cells capable of driving tumour formation with as few as 200 cells." (PMID 20332776, 2010). "Progressive genome modulation in the CD44+/CD24-/low subpopulation of the breast cancer cell line MDA-MB-468 leads to different coexisting subclones." (PMID 20199686, 2010). "For instance, mammosphere cells were found to enrich breast cancer stem-like cells with the phenotype of CD44+CD24-." (PMID 20569497, 2010). "Phillips and colleagues also demonstrated the radioresistance of putative breast cancer stem/progenitor cells by comparing the radiosensitivity of cells derived from the CD44+/CD24-subpopulation of MCF-7 cell line grown as spheres vs. monolayers." (PMID 20615238, 2010). "Treatment of breast cancer cells with metformin led to a reduced CD44-high/CD24-low population, decreasing the ability of breast cancer stem cells to form mammospheres." (PMID 24281219, 2010). "Cancer cells that display the cell surface marker profile of CD44+/CD24-/Lineage- were the first described tumorigenic progenitor cell types for breast cancer." (PMID 20691079, 2010). "Several breast cancer cell lines were sorted with CD24 and CD44, known markers for enrichment of breast cancer TICs." (PMID 19997106, 2010). "Breast carcinomas have been reported to contain a subpopulation of CD44+/CD24– tumor cells with stem-cell-like properties." (PMID 21050424, 2010). "Several other studies have used putative CSC markers such as CD44+/CD24-/low to identify similar populations within breast cancer cell lines, but given that CD44 is a basal marker, this phenotype did not isolate the tumorigenic population." (PMID 19555472, 2009). "For example, CD34+CD38- cells in leukemia, CD44+CD24low/lin- cells in breast cancer and CD133+ cells in brain and prostate tumors." (PMID 19744348, 2009). "The finding that CD44+ cells play a key role in chemoresistant breast cancer recurrences provides an innovative strategy to improve breast cancer treatment." (PMID 19240712, 2009). "Here, we show that antibody-mediated CD44-targeting in human breast cancer xenografts (HBCx) significantly reduces tumour growth and that this effect is associated to induction of growth-inhibiting factors." (PMID 19240712, 2009). "Breast cancer cell lines were sorted into CD44posCD24pos and CD44posCD24neg populations to evaluate their progeny for the expression of CD44, CD24, and markers of a mesenchymal phenotype." (PMID 19906290, 2009). "Originally, these tumor-driving cells were identified as a fraction of breast cancer cells with high and low expression of the cell-surface markers CD44 and CD24, respectively." (PMID 19583841, 2009). "While CD44neg/lowCD24pos cells lack the ability to give rise to their invasive CD44posCD24neg counterpart, the regulation of CD24 and the invasive, CD44posCD24neg phenotype in CD44 positive breast cancer cells is less well understood." (PMID 19906290, 2009). "In conclusion, we show here for the first time that targeting CD44+ breast cancer cells inhibits tumour growth and post-chemotherapy tumour recurrence in both ER+ and basal-like breast cancer." (PMID 19240712, 2009). "In cell lines from mammary tumors Brca1 knockout mice, the expression of CD133 cells is associated with stem cell properties as well as CD44+/CD24-/low phenotype." (PMID 19555472, 2009).
breast carcinoma (continued). "Notedly, the frequency of CSCs in the CD44-positive fraction of HNSCC was one order of magnitude below CSCs from colon or breast carcinomas." (PMID 18852874, 2008). "Recent studies identified putative human breast cancer stem cells by CD44+/CD24low cell surface markers that correspond to normal mammary gland-initiating cells in the mouse model." (PMID 18394172, 2008). "Taken together, these data show that CD44+/CD24-/ESA+ cells in breast cancer lines exhibit increased resistance to chemotherapy, providing evidence for a mechanism of post-treatment recurrence." (PMID 18366788, 2008). "Cell lines derived from a tumor with EMT features, 0_A1, lost expression of keratins, and contained a distinct subpopulation of breast cancer stem cells that express CD44+/CD24- markers." (PMID 18394172, 2008). "CD24low/- CD44+ has been suggested to define a population of cells that contain potential breast cancer stem cells, as has high expression of α-6 integrin." (PMID 18541018, 2008). "In human breast cancers, these tumorigenic breast cancer stem cells are enriched in cells with a CD44+/CD24-/low/ESA+ phenotype." (PMID 18366788, 2008). "A population of CD44+/CD24-/low cells has been demonstrated to have tumor-initiating properties in breast cancer." (PMID 18559090, 2008). "We correlated the presence of CD44+/CD24- cells to two gene signatures with prognostic value specific for either CD44+ or CD24+ breast cancer cells published by Shipitsin and colleagues." (PMID 18559090, 2008). "Second, some Brca1-deficient tumors contain CD44+/CD24-/Low cells, previously associated with human breast cancer stem cells, whereas others contain CD133+ cells previously associated with tumors in other organs." (PMID 18241344, 2008). "These cells were positive for CD44, a marker that has been suggested to be expressed on breast cancer stem cells." (PMID 19087284, 2008). "Although the expression of CD44 has been attributed to a cancer stem cell-like phenotype and found to increase the invasive properties of breast cancer cells, its role and prevalence in metastasis have been controversial." (PMID 19087284, 2008). "Brca1-deficient mouse mammary tumors harbor heterogeneous cancer stem cell populations, and CD44+/CD24- cells represent a population that correlates with human breast cancer stem cells." (PMID 18241344, 2008). "Similar to primary breast cancers, cell line derived tumor-initiating cells are enriched in cells with the CD44+/CD24-/low/epithelial-specific antigen (ESA)+ phenotype." (PMID 18366788, 2008). "We demonstrate an association of the CD44+/CD24- phenotype to basal-like and BRCA1 hereditary breast cancer." (PMID 18559090, 2008). "We have explored the prevalence of cells with different CD44/CD24 phenotypes within breast cancer subtypes." (PMID 18559090, 2008). "Since BrCSCs have been identified as CD44+CD24- subpopulation from breast cancer patient samples, much progress in research on this field has been achieved." (PMID 18477410, 2008). "Using in vitro-separated tumorigenic cells from malignant human breast cancer-derived pleural effusions, Al Hajj and colleagues isolated a cell population characterized by high CD44 expression and low or undetectable levels of CD24 (CD44+CD24−/low)." (PMID 18682804, 2008). "By using an affinity column constructed by immobilizing E-selectin/Fc recombinant, the E-selectin binding protein that mediated breast cancer cell transendothelial migration was identified as human CD44." (PMID 18350162, 2008). "Contradictive to results by Al-Hajj and colleagues demonstrating CD44+/CD24- cells in all their breast cancer samples, we only detected cells with this phenotype in 31% of our tumors." (PMID 18559090, 2008). "An elevated concentration of HA and CD44 is related with the genesis of tumors; CD44, therefore, is considered as a tumor marker, mostly for urologic and breast cancers." (PMID 18568197, 2008).
breast carcinoma (continued). "All cell lines derived from another mammary tumor exhibited low levels of CD44+/CD24- cells, but they harbored 2% to 5.9% CD133+ cells, which were previously associated with cancer stem cells in other human and murine tumors." (PMID 18241344, 2008). "Recently, one study has shown that MMP9 forms a complex with the hyaluronan receptor CD44 on the surface of breast cancer cells and activates downstream TGF-β, facilitating tumour cell survival, invasion and metastasis." (PMID 17242701, 2007). "We show that a subgroup of breast cancer cell lines with a higher percentage of CD44+/CD24- cells express higher levels of proinvasive genes and invade matrigel in vitro." (PMID 17062128, 2006). "Although most studies have shown CD44-mediated invasion of breast cancer cells, Lopez and coworkers showed inhibition of breast cancer metastasis by this molecule." (PMID 17062128, 2006). "Breast cancer cells with CD44+/CD24- subpopulation express higher levels of proinvasive genes and have highly invasive properties." (PMID 17062128, 2006). "In this report we show the relationship between CD44+/CD24- phenotype of breast cancer cells and discrete steps of the metastatic cascade." (PMID 17062128, 2006). "A subpopulation (CD44+/CD24-) of breast cancer cells has been reported to have stem/progenitor cell properties." (PMID 17062128, 2006). "A report has shown that the long non-coding RNA (lncRNA) ELEANORS is exclusively expressed in ER+ breast cancers, where it has been implicated in relapse-promoting activity and upregulation of a breast cancer stemness gene, CD44, which helps maintain the tumor stem population and dormancy." (PMID 40977686, 2025). "Furthermore, ER+ breast cancer cells with high levels of CD44 show increased phenotypic plasticity and resistance under ET pressure." (PMID 40410608, 2025). "Notably, Al-Hajj’s 2003 study successfully isolated CD44+CD24−/low CSCs from breast cancer, which exhibited robust tumorigenic potential in xenograft models." (PMID 40430852, 2025). "Regarding gene therapy strategies, complementary DNA (cDNA) vaccine to CD44 variant isoforms, but not CD44s, demonstrated decreased tumor growth, aggressiveness and metastasis in breast cancer xenografts." (PMID 40114966, 2025). "Notably, overexpression of CD44 has been shown to increase the levels of Nrf2 in human breast cancer stem-cell-like cells; the Nrf2 levels were further increased by HA treatment, whereas CD44 depletion had the opposite effect." (PMID 41002415, 2025). "Additionally, nanoparticle-mediated delivery of therapeutic agents, such as doxycycline, has demonstrated significant potential for overcoming MDR in CD44-overexpressing MCF-7 breast cancer cells, offering a promising approach to targeted chemotherapy." (PMID 40363706, 2025). "Furthermore, it has been suggested that exposure to 5-FU induces the expression of CD44, a stem cell marker of breast cancer, in MDA-MB-231 cells." (PMID 40570957, 2025). "Studies have shown that CD44 cleavage is widespread across various malignancies, with ectodomain cleavage detected in 58% of gliomas, 67% of breast carcinomas, 90% of colon carcinomas, and other cancers, including non-small cell lung carcinoma and ovarian carcinoma." (PMID 41440277, 2025). "An important effect of loss of PRLR expression in HR + MCF7 breast cancer cells were the promotion of luminal-to-basal conversion as measured by the loss of expression of the luminal markers CK18 and ER and the gain in stem cell marker CD44 expression." (PMID 40157909, 2025). "Additionally, CD44-positive breast cancer TICs can be precisely targeted by gemcitabine-conjugated nanoparticles functionalized with CD44 antibodies, improving overall therapeutic efficacy." (PMID 40777043, 2025). "The tumor samples from breast cancer patients with bone metastasis exhibited overexpression of CD44, leading us to speculate that CD44 may facilitate the colonization of breast cancer cells in bone." (PMID 40500539, 2025).
breast carcinoma (continued). "In addition, CD44-targeted and pH-sensitive doxorubicin-loaded micelles have exerted selective cytotoxic effects in breast cancer xenografts, resulting in apoptosis induction." (PMID 40114966, 2025). "To furtherverify whether the high binding affinity of AKPC-siYTto breast cancer cells was CD44 dependent, we generated HCC38 andMDA-MB-231 cell lines with stable CD44 knockdown by using a lentiviraltransduction system." (PMID 40176316, 2025). "Compared to MC3-LNPs, AKPC-LNPs exhibited significantlyhigher silencing potency of YAP, TAZ, and both, indicating that AKPC-LNPscan efficiently deliver siRNA to CD44+ breast cancer cells.We also measured the mRNA expression of YAP/TAZ downstream genes AMTOL2,CTGF, and CYR61 in breast cancer cells." (PMID 40176316, 2025). "Clinical studies have also hinted at the impact of doxycycline on the cancer stem cell compartment; pre-operative administration of the drug to patients with breast cancer led to reduced expression of the stemness markers CD44 and ALDH1 in tumors compared with matched pre-treatment biopsies." (PMID 39796759, 2025). "However, successful interventions in other CD44-driven malignancies—including head and neck squamous cell carcinoma, breast cancer, osteosarcoma, and leukemia —provide a compelling rationale for investigating similar approaches in TC." (PMID 40363706, 2025). "Interestingly, the interaction between CD44 intracellular domain and AP-1 promotes CD44 expression in breast cancer cells." (PMID 40260916, 2025). "As CD44 positively regulates the proliferation of breast cancer cells, we investigated whether combining the two drugs in concentrations affecting CD44 levels would have an impact on MDA-MB-231 cell propagation." (PMID 40806710, 2025). "To address this, we isolated BCSCs from the ER+ breast cancer cell line MCF7 using two methods: flow cytometry gating on ESA+CD24low/CD44+ cells and functional isolation by anoikis-resistance (AR) which is dependent upon survival in anchorage-independent conditions." (PMID 39695328, 2025). "This study was conducted to assess the expression of CD44 in breast cancer tissue." (PMID 40881916, 2025). "It is also reported that direct binding of STAT3 with CD44 and NF-kB increases CD44 expression via human telomerase reverse transcriptase-mediated autocrine signaling in the breast cancer cell lines, which can contribute to promote a cancer stem cell phenotype." (PMID 40021617, 2025). "The apparent independence of these features in ET-resistant breast cancers prompted us to investigate potential interactions between CD44 and SLC1A2, hypothesizing that they might share regulatory mechanisms." (PMID 40410608, 2025). "Additionally, in models of breast cancer, doxycycline reduces both the formation of mammospheres and the CD44+ cancer stem compartment." (PMID 39796759, 2025). "Recent in vitro investigations have elucidated that CD147 facilitates the assembly of a multiprotein complex comprising CD147, CD44, and EGFR in lipid raft-associated microdomains of the cell membrane, thereby enhancing the invasion of breast cancer cells such as MDA-MB-231 and MCF-7." (PMID 41479915, 2025). "Moreover, the association of kaempferol with verapamil inhibits chemoresistance in breast cancer stem cells through the dysregulation of CD44+-NANOG-MDR1 pathways." (PMID 39859345, 2025). "Targeting different CD44 isoforms or inducing CD44 alternative splicing may be a favorable treatment strategy for breast cancer." (PMID 38783892, 2024). "Additionally, in human breast cancer cells, silencing CD44 was also shown to decrease the glycolytic phenotype of cancer cells via regulating c‐Src/AKT/LKB1/AMPKα/HIF‐1α signaling." (PMID 38783892, 2024). "We demonstrated that NP-ICG-HAscan bind to 4T1 breast cancer cells through CD44/HA interactions.Moreover, NP-ICG-HAs target CD44 expressing breast tumors in the MMTV-PyMTmouse model, and CD44 expressing breast cancer cells in the lung in4T1 inoculated BALB/c mice." (PMID 38757711, 2024).